VIM (vimentin)
Diseases named in the same sentence as VIM in open-access papers (continued):
Sharing a sentence is not in itself a finding about the gene and the disease.
Retinal atrophy (1 paper, 2025). A nonspecific term denoting wasting, especially as a result of degeneration, of the retinal pigment epithelium (RPE) and neurosensory retinal cells. "Likewise, the expression of vimentin, a Müller glia marker, was reduced with time, further suggesting broader retinal atrophy." (PMID 41210963, 2025).
retinal ischemia (1 paper, 2017). A ischemic disease that involves the retina. "In comparison to the control retina (Sham), anti-vimentin immunoreactivity was also enhanced after retinal ischemia and preischemia administration of vehicle (Vehicle + I/R)." (PMID 28709426, 2017).
retinal vein occlusion (1 paper, 2023). An occlusion of the retinal vein. "Proteins that were upregulated in our study and in experimental retinal vein occlusion included fibronectin, annexin A1, galectin-3, alpha-crystallin B chain, vimentin, annexin A2, STAT1, GFAP, osteopontin, vitronectin, and clusterin." (PMID 37175625, 2023).
rhabdomyoma (1 paper, 2013). A benign mesenchymal tumor arising from skeletal or cardiac muscle. "The adult rhabdomyoma showed variable immunoreactivity for vimentin, S100, and smooth muscle actin." (PMID 24288631, 2013).
rosacea (1 paper, 2023). A chronic erythematous skin disorder that affects the face. "The early upregulation of α-SMA and vimentin may be caused by the proliferation of capillaries, and the increase in type I collagen appeared on the 20th day, indicating that the long-term LL-37-induced model of rosacea may involve myofibroblast proliferation and fibrosis." (PMID 37185701, 2023).
Salmonella Infections (1 paper, 2023). Infections with bacteria of the genus SALMONELLA. "To determine whether there is a causal relationship between vimentin rearrangement and Salmonella infection, we used the CRISPR/Cas9 method to establish vimentin-knockout (KO) cells and the lentiviral system to construct vimentin KO-full length (FL) rescue cells." (PMID 36717589, 2023). "Taken together, these results showed that vimentin plays a critical role in Salmonella infection by maintaining normal SCVs morphology." (PMID 36717589, 2023). "Imaging-based screen and permutational and combinational assays revealed a SopB-Cdc42-MEK1/2 signaling axis that controls vimentin remodeling upon Salmonella infection, for SCV organization." (PMID 36717589, 2023). "In this work, we demonstrated that Salmonella infection induced massive rearrangements of vimentin to encage SCV, and vimentin ablation led to dispersal of SCVs and decreased intracellular bacteria replication." (PMID 36717589, 2023). "In this study, we report the spatio-temporal rearrangement of vimentin filaments and their crucial role during Salmonella infection." (PMID 36717589, 2023). "Together, these results suggested that MEK1/2 inhibition (e.g., by Trametinib) targeting vimentin/SCV can potently inhibit Salmonella infection in vitro." (PMID 36717589, 2023). "To explore how vimentin functions in Salmonella infection, we performed co-immunoprecipitation (co-IP) with vimentin antibody in Salmonella infected cells to identify Salmonella proteins interacting with vimentin." (PMID 36717589, 2023). "Our data, however, show that activated Cdc42 induces vimentin enrichment around replication vacuoles in Salmonella infection." (PMID 36717589, 2023). "Together with the finding that SopB activates Cdc42, these results suggest that SopB-Cdc42-vimentin signaling axis is critical for maintaining concrete SCV during Salmonella infection." (PMID 36717589, 2023). "Nevertheless, for the specific mechanism, we cannot evade a possibility that Trametinib may have additional effects on Salmonella infection bypassing bacterial SopB or host vimentin filaments, which is an interesting follow-up study in the near future." (PMID 36717589, 2023). "To study whether host cytoskeletal proteins respond to Salmonella infection, we examined the vimentin network using an established model with human osteosarcoma cells (U2OS) that express abundant cytoskeletal filaments and are highly permissive to bacterial infection." (PMID 36717589, 2023). "However, vimentin markedly rearranged from 12 h post infection (hpi) upon Salmonella infection." (PMID 36717589, 2023).
sarcomatoid squamous cell carcinoma (1 paper, 2024). A poorly differentiated squamous cell carcinoma characterized by the presence of malignant cells with spindle cell features. "Immunohistochemical (IHC) markers vimentin and AE1 or AE3 are particularly useful in confirming oral sarcomatoid squamous cell carcinoma." (PMID 39211661, 2024).
scrapie (1 paper, 2016). A fatal disease of the nervous system in sheep and goats, characterized by pruritus, debility, and locomotor incoordination. "Initially we quantified the amount of detectable gliosis in the thalamus of preclinical scrapie-infected mice, using Gfap and Vimentin as markers of astroglia, and Gpr84 and Cx3cr1, as markers of microglia." (PMID 27046083, 2016).
serous cystadenoma (1 paper, 2023). A serous neoplasm in which the cysts and papillae are lined by a single layer of cells without atypia, architectural complexity or invasion. "In addition, a benign case histologically confirmed to be serous cystadenoma, was included as numerous vimentin positive CTC-like cells were present in the patient’s enriched samples." (PMID 36781954, 2023).
Sertoli cell tumor (1 paper, 2016). A sex cord-stromal tumor of the testis or the ovary. "Intermediate filaments in Sertoli cells of postnatal mice are comprised of Vimentin, which is also a Sertoli cell tumor marker." (PMID 27861152, 2016).
skeletal muscle tumors (1 paper, 2025). "AE1/AE3 serves as an epithelial tumor marker, Vimentin identifies fibroblasts, CD68 highlights monocytes, histiocytes, osteoclasts, mast cells, and giant cells, and Desmin is specific for skeletal muscle tumors." (PMID 41333207, 2025).
skin aging (1 paper, 2013). The gradual irreversible changes in structure of skin that occur as a result of the passage of time.. "Similar reports showed that AGEs bind to fibroblasts cell membranes receptors and interact with intracellular vimentin filaments, with DNA, contributing to the progression of skin aging." (PMID 24116020, 2013).
spindle cell lipoma (1 paper, 2005). A benign circumscribed tumor composed of spindled cells, adipocytes, and collagen bundles. "Spindle cell lipoma does not show any positivity for smooth-muscle actin, desmin or vimentin." (PMID 16281980, 2005).
squamous cell carcinoma of the vulva (1 paper, 2022).
squamous papilloma (1 paper, 2009). A benign epithelial neoplasm characterized by a papillary growth pattern and a proliferation of neoplastic squamous cells without morphologic evidence of malignancy. "The squamous papilloma was immunohistochemically positive for various cytokeratins and negative for vimentin and other antigens examined." (PMID 27956961, 2009).
sweat gland carcinoma (1 paper, 2024). A carcinoma arising from the sweat glands. "This study documents the first case of endocrine mucin-producing sweat gland carcinoma (EMPSGC) in a dog, successfully differentiating it from other apocrine gland tumors and MGC using immunohistochemical markers such as CK19, Sox9, CK5, p63, and vimentin." (PMID 39765541, 2024).
sweat gland tumors (1 paper, 2024). "Immunohistochemically, the myoepithelial markers commonly used in sweat gland tumors include CK5, vimentin, and p63." (PMID 39765541, 2024).
synucleinopathy (1 paper, 2025). A neurodegenerative disease that is characterized by the abnormal accumulation of aggregates of alpha-synuclein protein in neurons, nerve fibers or glial cells. "Increased vimentin truncation was also observed in synucleinopathy mouse brains, detected by the N-terminal antibody." (PMID 40479066, 2025). "To assess the pathological relevance of these observations on vimentin in synucleinopathies, we extended the vimentin analysis to human postmortem putamen tissue derived from patients with sporadic PD and controls." (PMID 40479066, 2025).
tendinopathy (1 paper, 2017). "The images showed that most of the cultured cells from healthy samples and tendinopathy samples expressed the surface marker for vimentin (red) and tenomodulin (green), and had elongated appearances under microscopy." (PMID 28598390, 2017).
trypanosomiasis (1 paper, 2018). Infection with protozoa of the genus trypanosoma. "Anti-vimentin antibodieswere present in most American trypanosomiasis samples, but notably, they aremuch more present in acute (76, 9%) or clinical defined syndromes,especially cardiac disease (87, 9%)." (PMID 29538505, 2018).
tyrosinemia (1 paper, 2023). An autosomal recessive inherited metabolic disorder caused by mutations in the FAH, HPD, and TAT genes. "For instance, vimentin is a substrate of STK33 and participates in photoperiod regulation in the endocrine system; ERK2 is another substrate of STK33 and regulates tyrosinemia and tyrosinemia-associated neurological disorders." (PMID 37146716, 2023).
Umbilical hernia (1 paper, 2018). Protrusion of abdominal contents through a defect in the abdominal wall musculature around the umbilicus. "None of the polymorphisms detected in the four candidate genes outside the QTL-region on SSC14 (VCAN, MMP13, PYCR1 and VIM) obtained significant associations with umbilical hernia." (PMID 29843603, 2018).
uterine tumor (1 paper, 2024). "Similarly, within the subgroup of patients with no detectable extra-uterine tumor spread (FIGO stage 1), 93% (n = 1051) of the samples expressed vimentin, while the remaining 7% (n = 74) had loss of expression." (PMID 39516342, 2024).
Varicose veins (1 paper, 2021). Enlarged and tortuous veins. "The proliferation of SMCs associated with higher expression of vimentin and Notch ligands was found in varicose veins." (PMID 34944071, 2021).
viral myocarditis (1 paper, 2018). Myocarditis that is caused by an infection with a viral agent. "Anti-vimentin antibodies could be amarker of cardiac muscle cell inflammatory involvement, showed by AmericanTrypanosomiasis patients with active muscle cell damage and must be tested in othercardiac muscle inflammatory conditions as viral myocarditis." (PMID 29538505, 2018).
vulvar melanoma (1 paper, 2022). A usually pigmented, nodular or polypoid malignant neoplasm that originates from melanocytes and arises from the vulva. "Therefore, diagnosis of amelanotic vulvar melanoma requires IHC testing of HMB-45, protein S-100, vimentin, MART-1, and tyrosinase." (PMID 36358637, 2022).
vulvar sarcoma (1 paper, 2020). "EMC is an extremely rare subtype of vulvar sarcoma that is consistently positive for vimentin, variable positivity for S100 protein, neuron-specific enolase and synaptophysin, completely negative for CK, and harhor EWSR1-NR4A3 fusion in about 65% of cases." (PMID 31915021, 2020).
Yersinia pseudotuberculosis infection (1 paper, 2023). "For instance, bacteria-containing vacuole (BCV) formation during Yersinia pseudotuberculosis infection was significantly reduced in vimentin-depleted cells, strengthening the hypothesis that bacteria may generally require vimentin to maintain the stability of their replication vacuoles." (PMID 36717589, 2023).
tumor (3,986 papers, 1988 to 2026). "Although the myofibroblastic phenotype (α-SMA+/Vimentin+/CD34-) also increased overall with tumor grade and varied across acinar patterns, this association was comparatively weaker and less statistically robust than that observed for telocytes." (PMID 41683955, 2026). "During EMT, the loss of E-cadherin and upregulation of N-cadherin/vimentin are critical hallmarks of acquired tumor invasiveness." (PMID 41154358, 2025). "Upregulation of VIM was also associated with larger tumor size and more advanced clinical stage in primary tumors." (PMID 40529228, 2025). "The EMT is a critical process involved in tumor cell migration and is associated with inhibition of E-cadherin and raised levels of both N-cadherin and Vimentin, which are thus markers of the EMT." (PMID 40612679, 2025). "This subtype has been designated the mesenchymal cluster or normal-like/claudin-low and overexpresses genes associated with tumor invasive and aggressive features such as up-regulation of VIM, TGFB1 and SERPINE1/2 and cancer stemness such as CD44 expression." (PMID 38819630, 2025). "Vimentin staining confirmed expression not only in the tumor cells but also prominently in the tumor-associated microvasculature." (PMID 41009669, 2025). "TGF-β activates the Smad2/3 pathway, which initiates changes in tumor cell gene expression, leading to the loss of E-cadherin, increased vimentin expression, and increased cell invasiveness." (PMID 40362280, 2025). "Vimentin expression is also associated with resistance to apoptosis and increased tumor cell survival, and N‐cadherin can promote cell survival, resistance to apoptosis, and activate several signaling pathways that are involved in tumor progression." (PMID 40650414, 2025). "In particular, we found a retarded tumor growth that was associated with increased collagen deposition, reduced vimentin expression and inhibited migration of GBM cells in the presence of MSCMel." (PMID 40083939, 2025). "Tumour migration, invasion, and proliferation were significantly associated with E‐cadherin, vimentin, β‐catenin, MMP‐2, and MMP‐9." (PMID 40468625, 2025). "Vimentin expression was independently associated with tumor invasive and metastatic features, supporting its potential role as a prognostic marker." (PMID 40831933, 2025). "Although increased Vimentin expression in tumors is associated with tumor invasion and poor prognosis, its exact role in ABL progression remains controversial." (PMID 40457691, 2025). "Pbrm1 loss in preexisting PDAC shifted the tumor grade from a well- to a poorly differentiated state and elevated vimentin expression." (PMID 40454484, 2025). "Presence of α-SMA−Vimentin+ CAFs was associated with poor survival in PDAC patients, and high vimentin expression in tumour stroma was linked to high malignant potential and disease recurrence in colorectal cancer (CRC) patients." (PMID 39780187, 2025). "vimentin is associated with epithelial-mesenchymal transition and tumor invasiveness., and Ki-67 can be used as a marker of cell proliferation." (PMID 40831933, 2025). "Given the established association between Vimentin and tumor cell malignancy in numerous studies, Vimentin was chosen as the downstream gene of KLF5 in conjunction with RNA-seq data." (PMID 40307891, 2025). "The immunohistochemistry for detecting components of the tumor microenvironment reveled the infiltration of tumor-associated macrophages (CD68, CD163) and tumor-associated fibroblasts (vimentin, SMA) in the tumor sample." (PMID 40433378, 2025). "This review explores the diagnostic value of immunohistochemical surrogate markers, vimentin, synaptophysin, and histone H3 lysine 27 methylation (H3K27me), in distinguishing these tumor types." (PMID 40937216, 2025). "And Vimentin high-level expression is observed significant association with the tumor size (beta, 1.02 95% CI, 0.41–1.63; P =0.002)." (PMID 40831933, 2025).
tumor (continued). "The intermediate filament vimentin is associated with aggressiveness and is involved in the migration and polarity of tumor cells." (PMID 41310103, 2025). "Given the close association between EMT and tumour cell migration, our results revealed that C1orf131 knockdown caused an elevation of E-cadherin and a decline in N-cadherin, Vimentin, and Snail expression in A549 and H358 cells." (PMID 38928092, 2024). "It has been reported that high IHC-based expression of Vimentin is associated with the enhanced invasiveness and distant metastasis of PCa tumor cells, including bone metastasis." (PMID 38705879, 2024). "Lastly, RNF208 is directly implicated in Vimentin degradation and has been linked to the aggressiveness of various tumor cell lines, with its loss enhancing dissemination and metastasis spreading." (PMID 39199549, 2024). "Accordingly, Nijkamp and colleagues demonstrated a potential correlation between the loss of E-cadherin and the presence of vimentin, indicating increased migratory capabilities in tumor cells and an increased risk of metastasis in patients with HNSCC." (PMID 38611032, 2024). "The authors identified that tumor-associated endothelial cells secrete VIM through the unconventional type III protein secretion mechanism." (PMID 39766058, 2024). "In our drug-resistant cellular and in vivo tumor model, depletion of TF resulted a nearly complete loss of tumor cell surface expression of vimentin, a classical marker of EMT." (PMID 38191673, 2024). "At the mechanistic level, the expression of EBV latency genes, i.e., EBNA1 or EBNA3C, is associated with the upregulation of Vimentin and its subsequent association with tumor metastasis involving EMT72." (PMID 38705879, 2024). "In this context, the epithelial–mesenchymal transition (EMT), characterized by the loss of E-cadherin and gain of vimentin expression, is an important process in tumor progression." (PMID 39451592, 2024). "Consistent with the in vitro cell culture results, tumors with TF-depletion also downregulated levels of P-ERK and P-AKT and a nearly complete loss of tumor cell vimentin." (PMID 38191673, 2024). "The PN-to MES transition is recognized as the hallmark of malignant tumor progression, characterized by the upregulation of mesenchymal markers N-cadherin and Vimentin, and the downregulation of epithelial marker E-cadherin." (PMID 38576043, 2024). "Vimentin+ fibroblasts can be seen in close association with tumor acini, and areas of denser fibroblast presence are more apparent in maximum-intensity projections of whole-mount-IF-stained samples than in paraffin sections." (PMID 39610249, 2024). "Vimentin expression in the tumor stroma reflects higher tumor malignancy potential, and high vimentin expression in CRC is associated with advanced tumor stage, metastasis, and decreased survival." (PMID 39063041, 2024). "Tumor-associated endothelial cells actively secrete VIM through pro-angiogenic pathways through the type III unconventional protein secretion mechanism." (PMID 39766058, 2024). "E-cadherin, a transmembrane glycoprotein, participates in cell-cell adhesion and EMT, while Vimentin is highly expressed in mesenchymal cells and is positively associated with tumor metastasis." (PMID 38425243, 2024). "E-cadherin played an important role in tissue formation, tumor suppression, and Vimentin was closely associated with increased tumor cell invasiveness and metastasis, which both were the relevant marker of Epithelial-mesenchymal transition (EMT)." (PMID 39720592, 2024). "High expression levels of N-cadherin and vimentin are associated with enhanced tumor metastasis and invasion." (PMID 39440046, 2024). "Increased vimentin expression has been associated with tumor progression and metastasis in many cancers." (PMID 38338029, 2024).